CNR1 (cannabinoid receptor 1)
Diseases named in the same sentence as CNR1 in open-access papers (continued):
Sharing a sentence is not in itself a finding about the gene and the disease.
Cognitive impairment (67 papers, 2013 to 2025). Abnormal cognition is characterized by deficits in thinking, reasoning, or remembering. "CNR1 (AAT)n polymorphism was found to predict cognitive impairment, since the long AAT group had higher probability of failing more than two cognitive tests at equal values of age, disease duration, gender, education level and EDSS score." (PMID 24391723, 2013). "CNR1 genotype and cognitive impairment were also associated to each other when the analysis was restricted to those patients with less remarkable disability (EDSS<2.5) and shorter disease duration (years of disease<10)." (PMID 24391723, 2013). "Notably, the absence or reduction of receptors like signal regulatory protein α (SIRPα) and cannabinoid receptor 1 (CB1) on microglia, as well as the receptor CD2000 on neurons, can lead to an increased loss of synapses and cognitive impairment mediated by microglia and phagocytosis." (PMID 38259497, 2023). "Experimental studies showed that exposure to THC (Δ9-trans-Tetrahydrocannabinol; the main psychoactive compound in cannabis) goes along with an increase in CNR1 (CB1R) mRNA levels in rats, which was accompanied by symptoms of cognitive impairments." (PMID 35933470, 2022). "Significant CNR1 genotype-by-cannabis use interaction effects were observed on WM volumes and neurocognitive impairment in patients with SZ suggesting that heavy cannabis use in the context of specific CNR1 genotypes may contribute to confer WM abnormalities and cognitive impairment in SZ." (PMID 24133464, 2013).
Hepatic steatosis (62 papers, 2011 to 2026). Steatosis is a term used to denote lipid accumulation within hepatocytes. "In contrast, the liver steatosis reported when exposing zebrafish females to 4.2 μg/L DiNP was not only related to changes in the expression of cnr1, dagl, mgll, and lipid metabolism, but also to an increase in the orexigenic signals." (PMID 39595979, 2024). "In the two other transgenic zebrafish models described by Her’s group, hepatic steatosis is induced by liver-specific overexpression of yin yang 1 (YY1) or by cannabinoid receptor 1 (CB1R)." (PMID 23720231, 2013). "Our previous studies have demonstrated that Hepatitis B virus X proteins, gankyrin, Yin Yang 1 (YY1), and cannabinoid receptor 1 (CB1R) induce the development of hepatic steatosis by increasing the transcriptional activity of lipogenic gene expression in adult zebrafish." (PMID 29286302, 2017). "In the results of protein levels related to hepatic steatosis, HFD significantly increased liver cannabinoid receptor 1 and sterol-regulatory element binding protein 1 (SREBP-1)." (PMID 33182720, 2020). "Here, we demonstrate that a global knockout of the cannabinoid receptor 1 gene (CB1−/−) reduced the expression of the lipid droplet binding protein PLIN2 in the livers of CB1−/− and hepatitis B surface protein (HBs)-transgenic mice, which spontaneously develop hepatic steatosis." (PMID 31570772, 2020).
glioma (55 papers, 2008 to 2025). A benign or malignant brain and spinal cord tumor that arises from glial cells (astrocytes, oligodendrocytes, ependymal cells). "A retrospective molecular analysis of pediatric low-grade gliomas at one institute found that tumors that spontaneously involuted or remained stable had higher levels of the mRNA coding for CB1 (CNR1) than tumors that regressed." (PMID 35337156, 2022). "CNR1 expression has been reported in various glioma cell lines and receptor agonists trigger apoptosis and autophagy of these cells." (PMID 24662753, 2014). "The focus of the present research was to first determine CB1/CNR1, GPR55, and TRPV1 gene expression in glioma samples and in differentiated GBM cells and GSCs." (PMID 36497400, 2022). "First, we found up-regulated CNR1, GPR55, and TRPV1 expression in glioma patient-derived tissue samples and cell lines compared with non-malignant brain samples." (PMID 36497400, 2022). "In this study, in contrast to CNR1 and GPR55, TRPV1 mRNA negatively correlated with glioma grade and positively correlated with overall survival." (PMID 36497400, 2022). "In glioma tissues, highly expressed CNR1 and GPR55 did not correlate with increased malignancy." (PMID 36497400, 2022). "First, CNR1 and GPR55 mRNA expressions between different degrees of glioma malignancy, i.e., low-grade glioma vs. GBM, were not significantly different, but were higher than those in non-malignant brain." (PMID 36497400, 2022). "Highly expressed CNR1 and GPR55 genes in glioma and GBM vs. non-cancerous brain tissues did not correlate with increased malignancy or GBM subtype, respectively." (PMID 36497400, 2022). "CNR1 and GPR55 did not correlate with glioma grade, whereas TRPV1 negatively correlated with grade and positively correlated with longer overall survival." (PMID 36497400, 2022). "The relative expression of CNR1, GPR55 and TRPV1 genes in tissues showed that the three cannabinoid receptor genes did not correlate to each other in glioma or in GBM tissues, meaning they were independently regulated." (PMID 36497400, 2022).
diabetes (47 papers, 2010 to 2025). "Pb-B = − 77.411 allele A in rs1049353 gene CNR1 + 62.804 hypertension + 82.478 diabetes − 44.553 phosphorus ± 0.709." (PMID 32272684, 2020). "Finally, allele A in rs1049353 gene CNR1 and higher phosphorus concentration were independently associated with a lower Pb-B concentration, while hypertension and diabetes were independently associated with a higher Pb-B concentration." (PMID 32272684, 2020). "Rt-qPCR was used to evaluate the expression levels of CNR1, circRNAs, and miRNAs in 55 controls, 55 type 2 diabetes mellitus patients, and 55 DKD patients." (PMID 36987415, 2023). "In individuals with type 2 diabetes mellitus (T2DM), the cannabinoid receptor 1 (CNR1) gene polymorphism has been linked to diabetic nephropathy (DN)." (PMID 38406790, 2023). "Knockout of Cnr1 also contributes to a decrease in oxidative stress and inflammation induced by diabetes as compared to controls." (PMID 37408253, 2023).
epilepsy (46 papers, 2011 to 2025). A brain disorder characterized by episodes of abnormally increased neuronal discharge resulting in transient episodes of sensory or motor neurological dysfunction, or psychic dysfunction. "Cannabinoid receptor 1 (CB1R), a G-protein-coupled receptor, was reported to be a potential therapeutic target for many central nervous system diseases, such as ischemic stroke, epilepsy, and Parkinson's and Alzheimer's disease." (PMID 35251464, 2022).
breast cancer (43 papers, 2008 to 2026). A primary or metastatic malignant neoplasm involving the breast. "An early report on the antitumor effect of AEA has shown inhibition of MCF-7 and EFM-19 breast cancer cells via a cannabinoid receptor-1 (CB1)-dependent mechanism." (PMID 38254886, 2024). "Previous studies with human breast cancer cell lines demonstrated a positive correlation between CNR1 expression and the invasiveness of breast cancer." (PMID 33202602, 2020). "A novel agent named TXX-1-10 derived from rimonabant, an antagonist of cannabinoid receptor 1 with anticancer effects, has been discovered to reduce HPIP expression and has greater inhibitory effects on breast cancer cell growth and metastasis in vitro and in vivo than rimonabant." (PMID 34326318, 2021).
psychosis (42 papers, 2011 to 2026). "Specific CNR1 genotypes interacted with cannabis use to predict psychosis onset, with homozygous carriers showing greater risk (OR = 2.25, 95% CI: 1.12-4.53 for TT genotype with heavy cannabis use)." (PMID 41561992, 2025). "Genetic studies demonstrating gene-environment interactions (COMT, CNR1 polymorphisms moderating cannabis-psychosis associations) support biological vulnerability × environmental exposure models." (PMID 41561992, 2025). "While these data are consistent with the established role of the Cannabinoid receptor 1 in epidermal differentiation and skin development, and its involvement in psychosis risk and environmental insults sensitivity, new research in larger samples is needed." (PMID 39457583, 2024). "Rs806379 of the CNR1 gene showed a significant association with the phenotype of latency of psychosis after the first consumption of methamphetamine." (PMID 21886587, 2011). "In subjects with a first-episode of psychosis (FEP), another CNR1 polymorphism was associated with differential improvements in verbal memory and attention after 18 months of treatment." (PMID 39193030, 2024). "The genes encoding CB1R and CB2R (CNR1 and CNR2, respectively), have been proposed as candidate genes associated with psychosis and SZ." (PMID 39193030, 2024). "There was a significant difference in the allelic distribution of rs806379 of the CNR1 gene between the two subgroups divided by latency to onset of psychosis after methamphetamine abuse." (PMID 21886587, 2011). "Despite the preliminary nature of the sample, our findings point towards the role of genetic variants at CNR1 and CNR2 genes in the severity of the disorganized symptoms of first-episode psychosis and modulating cognitive performance conditional to cannabis use." (PMID 39193030, 2024). "The CNR1 gene encodes for the CB1 receptor, whose localization on different neuronal subpopulations specifically modulates emotional and social behavior, with potential implications for the psychosis phenotype." (PMID 37533248, 2024). "Finally, cognitive intermediate phenotypes of psychosis were found to differ depending on CNR1 genetic variation and its interaction with cannabis use." (PMID 37533248, 2024). "It has been previously reported that polymorphisms in cannabinoid receptor 1 gene, referred to as cannabinoid receptor 1 (CNR1), are associated with tendency to substance abuse and diseases like Alzheimer, psychotic disorders, alcohol dependence, and nicotine dependence." (PMID 32414087, 2020). "We also have identified differences in methylation in CNR1 by COMT genotype, which represent the epigenetic contributions of the environment to CNR1 expression in the course of normal human brain development and psychosis." (PMID 32433545, 2020).
colorectal cancer (41 papers, 2011 to 2025). A primary or metastatic malignant neoplasm that affects the colon or rectum. "In colorectal cancer, EVOO’s phenolics caused the upregulation of CB1 (cannabinoid receptor) by reducing DNA methylation at the CNR1 promotor, leading to decreased proliferation in Caco-2 cells." (PMID 40002421, 2025). "In human colorectal cancer cells, extra-virgin olive oil promoted the expression of the cannabinoid receptor type 1 (CNR1) gene encoding the cannabinoid receptor 1 (CB1) and suppressed cell proliferation." (PMID 37298797, 2023). "The up-regulation of miR-1273g-3p and its involvement in promoting cell migration, proliferation, and invasion via CNR1 gene have also been described in both lung and colorectal cancer cell lines." (PMID 32117716, 2020). "Consistently, CpG methylation of rat Cnr1 promoter, miR23a and miR-301a, previously shown to be involved in the pathogenesis of colorectal cancer and predicted to target CB1 mRNA, were reduced after administration of EVOO down to ~50% of controls." (PMID 26840281, 2016). "Following oil supplementation, the methylation of Cnr1 promoter, miR23a, and miR-301a, previously shown to be involved in the pathogenesis of colorectal cancer, was predicted to target CB1 mRNA and appears reduced." (PMID 26664449, 2015). "Moreover, colorectal cancer (CRC) proliferation has been shown to be mediated by the increased expression of CB1R through the transcriptional regulation of the CNR1 gene promoter." (PMID 40076652, 2025). "Furthermore, the observed CNR1 silencing in colorectal cancer is an interesting starting point for investigation on other cancer types." (PMID 35276827, 2022). "Interestingly, the frequency of CNR1 methylation is also quite high in human colorectal cancer and reaches about 77% and seems to be a relevant mechanism for cancer progression." (PMID 33530406, 2021). "Thus, dietary EVOO administration reduces the methylation status of rat CNR1 promoter and the expression of miR23A and miR-301a—two modulators of CB1 in the pathogenesis of colorectal cancer, thus inducing the selective expression of CB1 in rat colon." (PMID 32046164, 2020). "Greenhough and colleagues reported that induction of CNR1 and CNR2 in colorectal cancer cells inhibits tumorigenic RAS/MAPK and PI3K/AKT signaling, while the loss of CNR1 in tumor samples from colon cancer patients correlated with tumor growth." (PMID 33746610, 2021). "CB1 upregulation in this cellular model is particularly interesting since the CNR1 gene is silenced in colorectal cancer cells compared to normal colon mucosa cells (NCM460) and this gene has already been demonstrated to act as a tumor suppressor in vivo." (PMID 35276827, 2022). "In another system, similar opposing effects of the CB1 receptor (as a tumor suppressor) to GPR55 (as an oncogene) have been documented, in which DNA methylation of the CNR1 and GPR55 genes were also differentially regulated in samples from patients with colorectal cancer compared to control samples." (PMID 35666403, 2022).
steatosis (34 papers, 2010 to 2025). Increased lipid within the cytoplasm of cells. "On the other hand, CNR1 was recently implicated in the pathophysiology of acute and chronic liver conditions, including inflammation, fibrogenesis and steatosis." (PMID 24716593, 2014).
Parkinson disease (33 papers, 2008 to 2026). A progressive degenerative disorder of the central nervous system characterized by loss of dopamine producing neurons in the substantia nigra and the presence of Lewy bodies in the substantia nigra and locus coeruleus. "One of the hallmarks of Parkinson’s disease (PD) is the alteration in the expression and function of NMDA receptor (NMDAR) and cannabinoid receptor 1 (CB1R)." (PMID 38474266, 2024).
colitis (30 papers, 2010 to 2025). Inflammation of the colon. "Similarly, CNR1 has been documented to be downregulated in CD, and its activation confers protection against colitis by reducing inflammation." (PMID 38675452, 2024). "OM colitis has a vital neuronal component, as evidenced by elevated expression of mu- and delta-opioids, and the receptors NK1, cannabinoid receptor 1 (CB1R) and TRPA1, the receptor for OM and a member of the transient receptor potential channel family." (PMID 20615234, 2010).
type 2 diabetes (29 papers, 2012 to 2025). "Subcutaneous adipose tissue CNR1 gene expression levels were 2-fold elevated in type 2 diabetes subjects compared with control subjects." (PMID 27858284, 2017).
colon carcinoma (28 papers, 2013 to 2025). "The first study demonstrating the association of DNA hypermethylation of the CNR1 gene promoter contributing to the downregulation of CNR1 gene transcription was observed in colon cancer specimens." (PMID 36358910, 2022). "In addition, the stimulatory effect of phenolic extracts from EVOO and hydroxityrosol on cannabinoid receptor 1 (CB1) expression inversely correlated with DNA methylation at cannabinoid receptor 1 promoter and it was associated with reduced proliferation of human colon cancer cells." (PMID 29295516, 2017). "In human colon cancer cells (Caco-2), extra virgin olive oil (EVOO) stimulated the expression of CNR1 gene encoding for type 1 cannabinoid receptor (CB1) and reduced proliferation." (PMID 35015763, 2022). "Selective and transient upregulation of CNR1 gene expression was observed in human colon cancer cells (Caco-2) and rats exposed to short- and long-term dietary extra-virgin olive oil (EVOO) and its phenolic extracts (OPE) or authentic hydroxytyrosol (HT)." (PMID 36358910, 2022). "A recent investigation on colon cancer progression found CNR1 methylation increased at CpG islands surrounding the promoter region, whereas it was decreased in the body of the gene in tumor samples." (PMID 31143113, 2019). "In colon cancer Caco2 cells, EVOO and the individual compounds hydroxytyrosol and oleuropein were shown to increase CNR1 and CB1 expression associated with decreased methylation of the CNR1 gene." (PMID 29259973, 2017). "In other tumors, a role of CNR1 in invasion and metastasis has been reported and the endocanabinoid system has been reported as a promising tool to improve the efficacy of steroids in colon cancer." (PMID 24662753, 2014). "In the in vitro studies, EVOO extract, OHT and OPE were administered to human colon cancer cells (Caco-2) and CNR1 gene expression was evaluated by quantifying both CB1 mRNA and protein." (PMID 35276827, 2022).
neuroblastoma (27 papers, 2010 to 2025). Neuroblastoma (NB) is the most common solid, extracranial childhood tumor. "In mouse neuroblastoma cells, depletion of AP-3 results in increased cell surface expression of the cannabinoid receptor-1 (CB1R), suggesting a role for AP-3 in endosome to lysosome sorting or retention in endosomes." (PMID 29954076, 2018). "Indeed, the UCSC genome browser provides evidence that several of these transcription factors (i.e., NFkB, c-fos) bind to the CNR1 promoter region in neuroblastoma cell lines." (PMID 36674826, 2023). "Additionally, MAGEA9B, along with two other targets of HOXD-AS1 - TNF and CNR1, were recently found to be a part of neuroblastoma signature identified in several datasets." (PMID 25522241, 2014). "The model containing CNR1, PRKACB, CDKN3, and PCLAF can serve as a new prognostic biomarker for predicting the prognosis of patients with neuroblastoma." (PMID 40302936, 2025). "CNR1, PRKACB, CDKN3, and PCLAF were found to significantly affect the overall survival and event-free survival of neuroblastoma patients and were positively correlated with the INSS advanced stages." (PMID 40302936, 2025). "Four prognostic genes (CNR1, PRKACB, CDKN3, and PCLAF) were identified, and a prognostic model based on these genes was developed that provides novel insights into the prognostic evaluation of neuroblastoma." (PMID 40302936, 2025). "In experiments on NB-PDX3 cells, two additional specific CNR2 agonists, JWH133 and HU308, reduced neuroblastoma cell viability, whereas the CNR1 agonist ACEA did not, nor did antagonists of either CNR1 or CNR2 suppress neuroblastoma cell growth." (PMID 31900415, 2020). "We further found that neuroblastoma cells that were pre-treated with a CNR2 antagonist (SR144528) were protected against GW405833 (p = 0.014, Student’s t-test), while pre-treatment with a CNR1 antagonist (otenabant) had no protective effect." (PMID 31900415, 2020).
liver fibrosis (26 papers, 2010 to 2026). "Previous studies demonstrated that blocking the CB1 receptor by pharmacological antagonistslike RIM (SR141716A) or genetic inactivation like in Cnr1-/- mice limited theprogression of hepatic fibrosis whether the fibrosis was induced by bile ductligation, CCL4 or thioacetamide." (PMID 31389521, 2019). "Using iRNA mechanisms, CB1 (also known as CNR1) gene silencing can reduce liver fibrosis in knockout models and without the undesirable side effects of pharmacological antagonism." (PMID 32053633, 2020).
glioblastoma (25 papers, 2008 to 2025). The most malignant astrocytic tumor (WHO grade IV). "Three different glioblastoma cell lines were treated with specific cannabinoid receptor 1 and 2 agonists and antagonists." (PMID 30753211, 2019). "Cannabinoid-receptor 1 (CB1) and CB2-dependent mechanisms have been reported for anti-tumor activities of THC on glioblastoma cells." (PMID 37998380, 2023).